IL2 (interleukin 2)
Diseases named in the same sentence as IL2 in open-access papers (continued):
Sharing a sentence is not in itself a finding about the gene and the disease.
respiratory failure (9 papers, 2013 to 2024). The significant impairment of gas exchange within the lungs resulting in hypoxia, hypercarbia, or both, to the extent that organ tissue perfusion is severely compromised. "Interleukins like IL6, IL8 and IL2 along with TNFα might be main causative inflammatory leading respiratory failure." (PMID 32617527, 2020). "One patient assigned to the SBRT + IL-2 cohort developed respiratory failure after cycle 2 IL-2 characterized by patchy infiltrates in both lungs and outside the radiation ports in the right lateral and left anterior lung fields." (PMID 32467299, 2020). "Significantly increased SARS-CoV-2-induced IFN-γ, IL-2, and TNF-α production were seen in CD4 + T cells from patients with neurologic involvement and respiratory failure." (PMID 36093351, 2022).
squamous cell carcinoma (9 papers, 1992 to 2023). A carcinoma arising from squamous epithelial cells. "Local therapy with IL2 and human lymphokine-activated killer (LAK) cells also significantly reduced the growth of tumors in a nude mouse model of human squamous-cell carcinoma of the head and neck." (PMID 32560387, 2020). "While not inducing cytotoxicity on its own, IL-2 increased Vδ2 γδTc lysis of Daudi Burkitt’s lymphoma and TU167 squamous carcinoma cell lines in a dose-dependent manner in the presence of tumor cells or phosphoantigen." (PMID 28713391, 2017).
visceral leishmaniasis (9 papers, 2011 to 2022). A severe form of leishmaniasis characterized by irregular bouts of fever, substantial weight loss, swelling of the spleen and liver, and anemia (which may be serious). "In experimental visceral leishmaniasis, impairment of IL-2 production in T-cell anergic conditions circumvents the impaired innate immunity." (PMID 23027614, 2012). "Leish-111f induces increased CD4+ cells that produce IFN-γ, IL-2, and TNF-α, which confers desirable protection against visceral leishmaniasis with significant reductions in parasite loads." (PMID 35812381, 2022). "Control of visceral leishmaniasis in mice is believed to require IFN-γ, produced by spleen cells, which drives the immune response towards a Th1 phenotype by IL-2." (PMID 22563510, 2012).
amyloid (8 papers, 2021 to 2025). "IL2 has been reported to enhance astrocyte recruitment and activation of astrocytes and lead to decreased amyloid load in the mouse hippocampus." (PMID 35368255, 2022). "Another animal study reported that low-dose IL-2 treatment improved the amyloid pathology, synaptic failure, and memory function in AD mice." (PMID 34122046, 2021). "Regarding IL-2, it has been shown that this mediator can ameliorate amyloid pathology in mice with AD." (PMID 33540568, 2021).
chronic hepatitis B (8 papers, 2013 to 2025). "IL-2 is also produced by impaired CD8+ T cells in chronic hepatitis B." (PMID 38004743, 2023). "PBMC from chronic hepatitis B (CHB) patients were stimulated with HBV peptides (a panel representing well-defined HLA-A2-restricted epitopes or overlapping peptides (OLP) spanning the entire core protein), and cultured in IL-2-enriched medium supplemented with either IL-12 or IFN-α." (PMID 23516358, 2013). "Indeed, improving mitochondrial function by the anti-oxidant piperidine-nitroxide MitoTempo and IL-12 increased IFNγ release upon stimulation with HIV gag as well as CMV pp65, but did not affect the percentage of IFNγ, TNFα and IL-2 producing CD8 T cells as was observed in chronic hepatitis B." (PMID 39356699, 2024). "In contrast to previous observations in chronic hepatitis B, in PWH the percentage of IFNγ, TNFα and IL-2 producing CD8 T cells did not increase in the presence of MitoTempo and IL-12." (PMID 39356699, 2024).
chronic lymphocytic leukemia (8 papers, 2012 to 2025). "The first clinical trial dates back to the 2000s, when autologous leukemic B cells isolated from chronic lymphocytic leukemia (CLL) patients were transduced to express the human CD40L or IL-2 gene prior to cell reinfusion." (PMID 34576154, 2021). "Early experimental studies have revealed that IL-2 may serve as a survival factor for B-cell CLL (B-CLL) through the enhancement of antiapoptotic proteins, although high-dose IL-2 has been investigated as a therapeutic strategy for patients with CLL." (PMID 41333460, 2025). "For human chronic lymphatic leukemia (CLL) and B-cell lymphoid neoplasms, the immunostimulatory CpG-oligonucleotide DSP30 in combination with interleukin-2 (IL-2) has been reported to be an easy and efficient stimulus for metaphase generation." (PMID 22761949, 2012). "More recently, it has been reported in chronic lymphocytic leukemia (CLL) that patient-derived T cells treated with the NAE inhibitor MLN4924 showed a differential expression of NF‐κB‐regulated genes and downregulated IL-2 expression/signaling during activation." (PMID 37460534, 2023).
chronic myeloid leukemia (8 papers, 2015 to 2025). "With regard to TCR sensitivity, exogenous IL-2 restores basally depressed CD3ζ expression in patients with chronic myeloid leukemia." (PMID 29250063, 2017). "At the same time, de novo proteins have also been applied to improve the efficacy of treatment methods in hematological disorders, such as designing the novel structures of chimeric antigen receptors, new inhibitors for treating chronic myeloid leukemia, and the novel type of interleukin-2." (PMID 36829445, 2023). "However, in a clinical study of Dasatinib on chronic myelocytic leukemia (CML), patients taking Dasatinib had significantly reduced plasma IL-2 levels, suppressed STAT5 phosphorylation in Tregs cells, and TIM-3-mediated exhaustion of CD8+ T cells." (PMID 39372416, 2024).
diphtheria (8 papers, 2011 to 2024). A Gram-positive bacterial infection caused by Corynebacterium diphtheriae. "Mice which had received all three shots of Infanrix® IPV and were sacrificed 7 days after the third shot had significantly more diphtheria-specific CD4+ T cells producing IL-2, IL-6, or TNF-α when treated with GM-CSF than placebo-treated controls." (PMID 29961602, 2018).
fibrosarcoma (8 papers, 1993 to 2023). A malignant mesenchymal fibroblastic neoplasm affecting the soft tissue and bone. "Preclinical studies implicated the insertion of the IL-2 gene into retroviral and adenoviral vectors, and also, a pioneer study investigated the application of a retroviral vector for the delivery of IL-2 gene vector in order to cure a fibrosarcoma animal model." (PMID 36742134, 2023). "In the context of feline fibrosarcoma, adjuvant immunotherapy with local injection of recombinant human IL-2 extended survival times and local canarypox-vectored recombinant IL-2 immunotherapy significantly reduced recurrence rates in cat fibrosarcomas." (PMID 30947707, 2019). "In a different approach, the peritumoral injection of feline IL-2 or human IL-2 genes carried by poxviral vectors was assayed as adjunct treatment following surgery and 192Ir-brachytherapy for feline fibrosarcoma." (PMID 25506617, 2014). "Recently, recombinant human proteins such as Interleukin-2 (h-IL-2) has been used as a treatment option for cats with fibrosarcoma." (PMID 22666387, 2012). "Moreover, in the same study it was demonstrated that the weak antitumor effect of IL‐2 in Meth A fibrosarcoma bearing mice was enhanced by concomitant administration of 34 (10 mg/kg, 5 or 3 times per week) and IL‐2 (5 × 106 U/kg, 5 or 3 times per week) following 2 weeks of treatment." (PMID 30548868, 2019). "CRP, or its active peptide-fragment, when encapsulated in liposomes, were maximally effective in protecting not only metastases in a murine fibrosarcoma model, but increased survival when liposome-encapsulated CRP (or its peptide) were injected in combination with interleukin-2 (IL-2)." (PMID 34552600, 2021). "Here we demonstrate that the weakly immunogenic murine fibrosarcoma FS29 had reduced growth rate and in some cases was rejected by syngeneic animals, when modified to secrete either IL-2 or IL-4, but not IL-5." (PMID 8347485, 1993).
head and neck cancer (8 papers, 2011 to 2023). A primary or metastatic malignant neoplasm affecting the head and neck. "Collectively, these results show that Ad5/3-E2F-D24-hTNFa-IRES-hIL-2 is capable of replicating in and lysing several types of human head and neck cancer, with subsequent release of TNFα and IL-2, despite histology or tumor location." (PMID 35355980, 2022). "The results support our previous findings in expanded TIL from head and neck cancer patients, that expansion by high-dose IL-2 and CD3 antibody seems to support the continued expansion of bulk T-cell clones." (PMID 21773037, 2011). "The absence of IL2, thus, infers the characteristic of immune deficient head and neck cancer, including OSCC." (PMID 30564558, 2018).
Hodgkins lymphoma (8 papers, 2001 to 2024). A heterogeneous group of malignant lymphoid neoplasms of B-cell origin characterized histologically by the presence of Hodgkin and Reed-Sternberg (HRS) cells in the vast majority of cases. "To take advantage of the synergistic action, we incorporated IL2 and IL12 into a dual cytokine fusion protein linked to the anti-CD30-scFv antibody for targeting the cytokines toward Hodgkin's lymphoma cells." (PMID 23028547, 2012). "In addition, another study found that CXCR5+ICOS+CD8+ T cells show significant infiltration in tumor lymph nodes (LNs) of patients with Hodgkin’s lymphoma (HL) and could upregulate the expression of IL-2, IL-4, and IL-21, which promotes B-cell proliferation and antibody production." (PMID 38515134, 2024). "Since both HPS2 siblings developed NLPHL, cytolytic activity of polyclonal IL-2-activated NK cells was evaluated against human and murine tumor cell lines, including Hodgkin's lymphoma cell lines (L428 and L540 cell lines, HLA class I negative and positive, respectively)." (PMID 24302998, 2013). "This hypothesis was confirmed by our previously reported results, which showed strong negative correlations between the proportion of PB CD3+/CD152+ cells and proliferative activity, IL-2 and IFN-γ production in patients with Hodgkin's disease and healthy subjects." (PMID 15138491, 2004).
neutropenia (8 papers, 2007 to 2025). A decrease in the number of neutrophils found in the blood. "The mechanisms underlying RTX-induced respiratory tract infections are unclear, but abnormalities in IL-2 production and IL-2R expression, associated with decreased antigen-induced lymphocyte proliferation, late-onset neutropenia, and delayed onset cytopenia, are described." (PMID 38787037, 2024).
Opportunistic infection (8 papers, 2010 to 2023). An infection that is caused by a pathogen that would generally not be able to cause an infection in a host with a normal immune system. "The suppression of T-cell proliferation by ruxolitinib, likely through inhibition of JAK1 signaling by IL-2, may be associated with its increased rate of opportunistic infections in vivo." (PMID 31560729, 2019). "As a result, decreases in IL-2 and IFN-γ occur, leading to immunosuppressive effects and opportunistic infections, a marker of advanced disease." (PMID 28095491, 2017). "In this initial study, the only patient who did not normalize CXCR4 expression levels also failed to increase CD4+ T cell counts after IL-2 treatment and did not benefit clinically from the therapy, with continued occurrence of multiple opportunistic infections." (PMID 23383227, 2013). "Case reports suggested that recombinant IL-2 administration could raise CD4+ T cell counts in ICL patients and help improve the clinical outcome of opportunistic infections, including cryptococcal meningitis, chronic mycobacterial disease, and relapsing herpes zoster infection." (PMID 23383227, 2013).
oral cancer (8 papers, 2018 to 2025). "GSEA of CAFs activated by oral cancer-derived EVs revealed upregulation of several pathways linked to inflammation including TNFα, IL6_JAK_STAT3 pathway, and IL2_STAT5 signaling pathway." (PMID 37745296, 2023). "Based on a culture method similar to that used to activate lymphocytes for cell therapy performed on patients with oral cancer in our department, natural killer (NK) cells and cytotoxic T cells with strong cytotoxic activity were stimulated to proliferate with IL-2 in this study." (PMID 31768763, 2020). "In both tumor-bearing mice and oral cancer patients, heat therapy results in elevated lymphocyte transformation index (LTI), CD4+ cell counts, and significantly increased levels of interleukin-2 (IL-2) and tumor necrosis factor-α (TNF-α) activity." (PMID 39027362, 2024). "There are several ongoing studies with mAbs in oral cancers related to the key words (“oropharyngeal cancer” OR “oral cancer” OR “oral cavity cancer”) and (“cytokine therapy” OR cytokines OR IFN-α OR IL-2 OR TNF-α) from ClinicalTrials." (PMID 36209263, 2022). "The tobacco-related oral cancer is likely to be connected with multiple systemic immune impairs, especially defected CD4+ and CD3+ T cells and a differential regulation of IL-4 and IL-2 in CD8+ and CD4+ T-cell subsets in the peripheral blood." (PMID 31582940, 2019). "Over the previous three decades, IL-2 was identified and studied as a candidate for cancer immunotherapy, but its function in oral cancer progression and/or treatment has not been studied." (PMID 31117164, 2019).
osteoarthritis (8 papers, 2016 to 2025). A noninflammatory degenerative joint disease occurring chiefly in older persons, characterized by degeneration of the articular cartilage, hypertrophy of bone at the margins and changes in the synovial membrane. "Our notable results show that Fetuin-A mildly affects the development of osteoarthritis, on the grounds that only IL-2 levels were significantly lower in the Fetuin Group while CRP levels seemed significantly increased in the Fetuin Group." (PMID 31209645, 2019). "Pro-inflammatorycytokines (IL-1β, IL-6, and TNF-α) and anti-inflammatorycytokine (IL-2) levels in mouse models of osteoarthritis were evaluated,resulting in a reduction of serum expression of pro-inflammatory cytokinesand an enhancement of anti-inflammatory activity." (PMID 40300853, 2025).
toxoplasmosis (8 papers, 2018 to 2023). A parasitic disease contracted by the ingestion or fetal transmission of toxoplasma gondii. "Several previous studies have shown the correlation between the Th1 type immune response, characterized by the increase in IFN-γ and IL-2 production, and the enhanced resistance against toxoplasmosis in mice." (PMID 30564214, 2018). "It was also observed that pregnant women in the acute phase of toxoplasmosis (IgM+/IgG-) presented higher levels of TNF, IL-1β, IL-2, and IL-12." (PMID 36742306, 2023). "We found a pattern of increased TNF-α levels and low production of IL-2 and TGF-β production in the congenitally infected newborns, with disseminated toxoplasmosis and an inverse profile in those with localized lesions." (PMID 32231666, 2020). "Additionally, DNA vaccines encoding Toxoplasma MIC5 and MIC16 genes induced effective immunity, including enhanced levels of IgG, IFN-γ, IL-2, IL-12p70, and IL-12p40 and CD4+ and CD8+ T cells against toxoplasmosis." (PMID 35565525, 2022). "Our study is the first to show a protective effect of S4B6-containing IL2C pre-treatment in toxoplasmosis and our results suggest that IL2C pre-treatment can protect mice from lethal toxoplasmosis via distinct mechanisms, depending on the IL-2 mAb clone used to prepare the cytokine complex." (PMID 32753607, 2020). "Furthermore, a SPATR-based vaccine generated humoral and mixed Th1/Th2 type cellular immune responses inducing lymphocyte proliferation and cytokine (IFN-γ, IL-2, IL-4 and IL-10) secretion, showing that SPATR may be a promising vaccine candidate against toxoplasmosis." (PMID 35565525, 2022).
acute pancreatitis (7 papers, 2014 to 2025). An acute inflammatory process that leads to necrosis of the pancreatic parenchyma. "Inflammatory factors, such as IL-2, IL-6, and IL-10, are closely associated with acute pancreatitis." (PMID 38424643, 2024). "ROS produced by acute pancreatitis stimulate NF-κB, leading to excessive release of cytokines such as interleukin-1β (IL-1β), interleukin-2 (IL-2), interleukin-18 (IL-18), interleukin-6 (IL-6), and TNF-α." (PMID 40411704, 2025). "The role of IL-2 in burns and trauma has been actively stud-ied; however, there has been little effort to investigate the role of IL-2 in acute pancreatitis." (PMID 33803665, 2021). "One study confirmed that the level of IL-2 decreased in murine acute pancreatitis." (PMID 33803665, 2021). "During the first phase of acute pancreatitis, cytokine pro-inflammation, as TNF (tumor necrosis factor) α, interleukins (IL-1, IL-2, IL-18, IL-6) and chemokine, oxygen radical oxidant are released." (PMID 34036463, 2021). "Several signaling molecules (such as IL-1, IL-2, IL-6, PAF, substance P, TNF-α, MCP-1, and NF-κB) have been shown to play important roles in the progression of experimental acute pancreatitis." (PMID 25147563, 2014).
Anorexia (7 papers, 2015 to 2023). Lack of desire to eat (loss of appetite). "It is also known that high level of cytokines TNFα, IL-6, and IL-2 are associated with a decrease in food intake and may contribute to anorexia." (PMID 32297262, 2020). "A number of cytokines have been previously linked to anorexia, including IL-6, TNF-α, CXCL8, IL-1β, IL-18, IL-2, and IFN-γ." (PMID 32071269, 2020). "Severe lethargy, impaired memory, slowed responses, impaired attention, anorexia, lack of interest, and irritability are the symptoms found with most volunteers after receiving low doses of IL-2." (PMID 26403459, 2016).
asthenia (7 papers, 2011 to 2024). Clinical sign or symptom manifested as debility, or lack or loss of strength and energy. "Toxicities linked to vaccination plus IL-2 were mainly flu-like syndromes (grade I-II asthenia and fever) after IL-2 administration and local reactions in the vaccine injection sites." (PMID 23725550, 2013). "The most common side effects of IL-2 therapy are asthenia, fever, influenza-like syndrome, nausea, and vomiting." (PMID 37174716, 2023). "Overall, the most represented SOC among the reported events were general manifestations, consistent with the manifestations observed during IL-2 injection, such as asthenia, flu-like syndrome and pain at site injection, followed by gastrointestinal disorders." (PMID 34120214, 2021). "For the first 20 patients treated with higher-dose IL-2, the most common AE requiring the protocol amendment was grade >2 asthenia, which was reported in 11 patients (55%)." (PMID 21448165, 2011). "After treating the first 40 patients, a reduction in IL-2 dose to 3 MIU on 5 days per week, 2 weeks on followed by 2 weeks off, was necessary because of the onset of high rates of asthenia (55% of grade 3 or 4)." (PMID 21448165, 2011). "THD has synergistic and additive antiemetic, anti-asthenia, and analgesic effects of corticosteroids 57, 58; it inhibits the expression of cytokines without affecting levels of IL-2, IL-4, and IL-10 59, 60, thus offering the possibility of steroid-sparing or steroid-replacement therapy." (PMID 32489473, 2020).
autoimmune encephalitis (7 papers, 2015 to 2023). Inflammation of the brain secondary to an immune response triggered by the body itself. "Studies in patients with NMDAR antibody-associated autoimmune encephalitis have shown an increase in serum IL-2 and CSF IL-6, IL-17, CXCL-10, and IL-1β." (PMID 36048783, 2022). "Previous studies have shown that tocilizumab and low-dose IL-2 were effective in the treatment of refractory autoimmune encephalitis." (PMID 33408682, 2020). "Blocking Kvs reduces IL-2 and tumor necrosis factor production, resulting in improved autoimmune encephalitis and the inhibition of microglial-mediated neuronal death in experimental models." (PMID 25852770, 2015). "In addition, tocilizumab (an IL-6 inhibitor) and low-dose IL-2 are effective in the treatment of patients with refractory autoimmune encephalitis." (PMID 33408682, 2020).